EPHA2 (EPH receptor A2)
Diseases named in the same sentence as EPHA2 in open-access papers (continued):
Sharing a sentence is not in itself a finding about the gene and the disease.
osteosarcoma (23 papers, 2012 to 2025). A usually aggressive malignant bone-forming mesenchymal neoplasm, predominantly affecting adolescents and young adults. "Recently, we showed that EphA2 down-regulation is implicated in the synergistic antitumor activity of pazopanib and trametinib in preclinical models of osteosarcoma." (PMID 34831119, 2021). "We found that the gene encoding receptor tyrosine kinase EphA2, the ephrin type A receptor 2, is highly expressed in pediatric Ewing’s- and osteosarcomas." (PMID 23227212, 2012). "The upregulation of EphA2 in both human and canine osteosarcoma cells supported migration and invasiveness in vitro, likely mediated by integrin β3 expression, as confirmed by EphA2 silencing." (PMID 40563676, 2025). "More recently, enhanced cell proliferation and reduced apoptosis, leading to DR, were comparatively found in several human and canine osteosarcoma cell lines related to the overexpression of ephrin A2 (EphA2) receptor tyrosine kinase." (PMID 40563676, 2025). "EphA2 silencing was consistently associated with reduced activating phosphorylation of AKT, ERK1/ERK2, and SRC kinases in both human and canine osteosarcoma cells." (PMID 39056783, 2024). "We found that EphA2 is overexpressed in most of both canine and human osteosarcoma cell lines, while its silencing significantly reduced cell viability, migration, and invasion." (PMID 39056783, 2024). "DOX-siRNA JIP1 loading on EphA2-targeted carriers were very effective in inducing toxicity of osteosarcoma cells, which exhibit high level of EphA2 expression." (PMID 39596256, 2024). "To gain insight into the cytoplasmic signaling mechanisms utilized by EphA2, we assessed the activation status of multiple signaling pathways in both human and canine osteosarcoma cells." (PMID 39056783, 2024). "Collectively, our data suggest that targeting EphA2, either alone or in combination with chemotherapy, holds promise for improving outcomes in osteosarcoma patients." (PMID 39056783, 2024). "Our experiments revealed that silencing EphA2 expression in both canine and human osteosarcoma cells makes them more sensitive to cisplatin." (PMID 39056783, 2024). "To investigate the role of EphA2 in osteosarcoma cell migration, we used both wound healing and transwell migration assays." (PMID 39056783, 2024). "Our objectives were to assess EphA2 levels and its pro-malignant action in osteosarcoma cells of both species." (PMID 39056783, 2024). "In this study, we utilized a comparative approach to match EphA2 functions in human and canine osteosarcoma models." (PMID 39056783, 2024). "Collectively, these results suggest that EphA2 supports migration of both canine and human osteosarcoma cells in culture." (PMID 39056783, 2024). "Initially, a significant suppression of migration and proliferation properties was observed in four EPHA2-silenced osteosarcoma cell lines (HOS, KHOS/NP, MNNG/HOS and U2OS) compared to their controls." (PMID 35563562, 2022). "Chimeric Antigen Receptor-modified T (CAR T) cells that target EPHA2 have significant anti-tumor efficacy in vitro and can eradicate osteosarcoma tumors in vivo." (PMID 36077137, 2022). "The localization of ephrin type-A receptor 2 (EPHA2) was further validated using FACS analysis, which confirms the MS data of EPHA2 overexpression on the surface of osteosarcoma cells." (PMID 36077137, 2022). "Systemically injected CAR T cells targeting EPHA2 can traffic to and eliminate tumor deposits in murine livers and lungs in an aggressive metastatic osteosarcoma." (PMID 36077137, 2022). "In both the osteosarcoma and Ewing’s sarcoma data sets, a significant difference in EPHA2 expression levels was found in male (higher expression) vs. female (lower expression) subjects." (PMID 34831119, 2021). "To further investigate the role of EphA2 as an effective molecular target in bone sarcomas, we took advantage of the public gene database on osteosarcoma cell lines and patient cohorts to validate our data in silico." (PMID 34831119, 2021).
osteosarcoma (continued). "A significant correlation was found between EPHA2 expression and Huvos grade (osteosarcoma) and with worse overall survival (dedifferentiated chondrosarcoma)." (PMID 34831119, 2021). "Genome-wide microarray and immunohistochemistry studies demonstrated de novo expression of EphA2 in osteosarcoma patients as compared to healthy bone tissues." (PMID 34440844, 2021). "EPHA2 was highly expressed in the osteosarcoma (mean Z-score = 4.8), in Ewing’s sarcoma (mean Z-score = 3.9), and in chondrosarcoma (mean Z-score = 4.1) cell lines." (PMID 34831119, 2021). "In this study, we performed bioinformatic analyses in several databases (fully listed in the Methods section) to look for EphA2 expression and correlation with patients’ characteristics and clinical outcomes in osteosarcoma, Ewing’s sarcoma and chondrosarcoma." (PMID 34831119, 2021). "Taken together, these data derived from CCLE bioinformatic analyses demonstrate high EPHA2 expression levels in solid tumors, including in our histotypes of interest (osteosarcoma, Ewing’s sarcoma and chondrosarcoma)." (PMID 34831119, 2021). "Our investigation of EPHA2 expression with bioinformatic analyses and PDXs highlights the involvement of EPHA2 in the tumor biology of the three main bone sarcoma histotypes: osteosarcoma, Ewing’s sarcoma and chondrosarcoma." (PMID 34831119, 2021). "EphA2 silencing significantly reduced osteosarcoma cell proliferation and migration, while impeding MEK6 up-regulation in the treated cells significantly increased the antitumor effect of the studied drugs." (PMID 32531992, 2020). "As for EphA2, and in agreement with Fritsche-Guenther data, we confirmed the role of this protein in proliferation and migration of osteosarcoma cells using silencing experiments." (PMID 32531992, 2020). "To functionally validate the role of EphA2 in cell proliferation and migration, we performed silencing experiments in four osteosarcoma cell lines (HOS, KHOS/NP, MNNG/HOS and U-2 OS)." (PMID 32531992, 2020). "In all EphA2-silenced osteosarcoma cell lines, we detected a significant reduction in cell viability compared to scrambled controls (p < 0.05 in HOS and KHOS/NP, p < 0.01 in U-2 OS and p < 0.001 in MNNG-HOS)." (PMID 32531992, 2020). "High EPHA2 expression levels were also observed in pediatric osteosarcomas in a small number of samples (n = 3)." (PMID 23227212, 2012). "Our observations suggest that extending the targeting of EphA2 to human and canine osteosarcoma may reduce cells’ ability to evade elimination by cisplatin treatment while concurrently suppressing their invasive potential." (PMID 39056783, 2024). "Furthermore, inhibition of EphA2 expression led to a significant reduction in tumor development capability of canine osteosarcoma cells." (PMID 39056783, 2024). "Moreover, EphA2 silencing enhanced the sensitivity of osteosarcoma cells to cisplatin, a drug commonly used for treating this cancer." (PMID 39056783, 2024). "Additionally, while reduced expression of integrin β3 was observed in both human and canine osteosarcoma cells following EphA2 silencing, a reduction in N-cadherin expression was only observed in canine Eva cells." (PMID 39056783, 2024). "In addition to observing the effects of EphA2 silencing in cultured human and canine osteosarcoma cells, we also found that suppressing EphA2 activity significantly decreases tumor growth in xenograft models of canine osteosarcoma." (PMID 39056783, 2024). "In addition, USP3 promoted proliferation and metastasis of osteosarcoma cells by enhancing in vitro EphA2-mediated PI3K/AKT signaling pathway and in vivo tumor growth." (PMID 39596256, 2024). "This indicates that EphA2 contributes to reduced sensitivity to cisplatin in osteosarcoma and, therefore, may contribute to the development of drug resistance in this disease." (PMID 39056783, 2024).
osteosarcoma (continued). "Thus, our results underscore the importance of EphA2 in promoting osteosarcoma invasiveness, at least in part through the regulation of integrin β3 and associated signaling pathways." (PMID 39056783, 2024). "Collectively, our findings indicate that EphA2 promotes malignant behaviors in both human and canine osteosarcoma and that targeting EphA2, either alone or in combination with chemotherapy, could offer potential benefits to osteosarcoma patients." (PMID 39056783, 2024). "This suggests that EphA2 may support osteosarcoma cell survival by maintaining the activation of these pathways." (PMID 39056783, 2024). "In addition, higher measured levels of EPHA2 were indicative of advanced Huvos grade in osteoblastic osteosarcoma and poorer prognosis in patients with dedifferentiated chondrosarcoma." (PMID 35563562, 2022). "Interestingly, the de novo expression of EPHA2 in clinical osteosarcoma specimens and the proportional increase during progression from conventional to metastatic stages upgrades EPHA2 to a remarkable diagnostic biomarker." (PMID 35563562, 2022). "Osteosarcoma patients with EPHA2-positive tumors have a worse survival rate." (PMID 36077137, 2022). "Targeting EPHA2 is promising for the treatment of osteosarcoma." (PMID 36077137, 2022). "Likewise, the expression levels of EPHA2 were found to be significantly higher among male compared to female Ewing’s sarcoma and osteosarcoma patients, which was in accordance with the prognostic value of gender for those bone malignancies." (PMID 35563562, 2022). "EphA2 is up-regulated in osteosarcoma, Ewing sarcoma and rhabdomyosarcoma." (PMID 34440844, 2021). "However, notwithstanding all these caveats, our findings provide a strong rationale upon which to develop future research targeting EphA2 in osteosarcoma, Ewing’s sarcoma and chondrosarcoma." (PMID 34831119, 2021). "Next, we characterized EPHA2 expression and activation in bone sarcoma primary tissues and in patient-derived xenografts generated in our laboratory to verify their reliability as in vivo models of osteosarcoma, Ewing’s sarcoma and chondrosarcoma." (PMID 34831119, 2021). "In our previous work, we demonstrated that combined pazopanib + trametinib treatment could significantly reduce EphA2 expression in osteosarcoma cell lines and that this was possibly a relevant mechanism of response to the combination treatment." (PMID 34831119, 2021). "After 24 and 48 h of transfection, we demonstrated that down-modulation of EphA2 significantly reduced cell migration in all transfected osteosarcoma cell lines, compared to scrambled controls (p < 0.05 in HOS and MNNG-HOS, p < 0.01 in U-2 OS and p < 0.001 in KHOS/NP)." (PMID 32531992, 2020). "In addition, surface proteomic analysis of osteosarcoma has identified a wide range of proteins with differential abundance on osteosarcoma cells and human primary osteoblasts including ephrin type-A receptor (EPHA2)." (PMID 33303017, 2020). "Consequently, EphA2 system may contribute to the pathogenesis of osteosarcoma by modulating the communications between tumour cells and their microenvironment." (PMID 24599309, 2014). "As shown in osteosarcoma cells, overexpression of USP3 decreased EphA2 ubiquitination and stabilized EphA2 protein, whereas USP3 depletion enhanced ubiquitin-mediated EphA2 degradation." (PMID 39596256, 2024). "More recently, microvesicles (MVs) coated with surface-carboxyl Fe3O4 superparamagnetic nanoparticles (SPIONs) conjugated with EphA2-targeted peptides (YSAYPDSVPMMS, YSA) were designed and used to treat osteosarcoma." (PMID 39596256, 2024). "Currently, potential effective targets for CAR-T cell therapy in osteosarcoma include HER2, IGF1R, ROR1, EphA2, CSPG4, folate receptor with EC17, B7-H3, GD2, NKG2D, ALCAM/CD166, IL-11Rα, and FAP." (PMID 38187386, 2023). "We injected the LM7 osteosarcoma cell line into the peritoneum of NSG mice, followed by injection of T cells engineered to express an EphA2-specific CAR." (PMID 36002574, 2022).
osteosarcoma (continued). "Mostly, the upregulation of EPH receptors leads to tumor-promoting functions in bone sarcomas such as tumor cells migration and proliferation by EPHA2, along with enhanced carcinogenesis and invasion by EPHA7 in osteosarcoma." (PMID 35563562, 2022). "From the functional standpoint, binding of ephrinA1 to EphA2 activates the oncogenic MAPK signaling and stimulates osteosarcoma metastasis." (PMID 34440844, 2021). "As a first step, we explored EPHA2 gene expression levels in the whole Cancer Cell Line Encyclopedia (CCLE), which included 10 osteosarcoma, 12 Ewing’s sarcoma and 4 chondrosarcoma cell lines." (PMID 34831119, 2021). "Pazopanib + trametinib demonstrated synergistic antitumor effects in osteosarcoma models through ERK and Akt inhibition and EphA2 and IL-7R down-modulation." (PMID 32531992, 2020). "To validate these findings, we checked MEK6, EphA2, and IL7R also at protein level in all seven osteosarcoma cell lines after 24 h of treatment with pazopanib (10 μM), trametinib (25 nM), and their combination." (PMID 32531992, 2020). "Additionally, in vivo EphA2‐CAR‐NK cells showed promising anti‐cancer activity in rhabdomyosarcoma and osteosarcoma mouse models." (PMID 39763064, 2025). "Significantly, EphA2‐specific CAR‐NK cells demonstrated enhanced cytotoxic activity against several paediatric sarcoma cell lines in vitro, including those of rhabdomyosarcoma, Ewing sarcoma and osteosarcoma, compared to unmodified NK cells." (PMID 39763064, 2025). "EphA2‐specific CAR‐NK cells exhibit superior cytotoxicity against sarcoma cell lines in vitro and demonstrate significant anti‐tumour activity in in vivo mouse models of rhabdomyosarcoma and osteosarcoma." (PMID 39763064, 2025). "Analyses of the resazurin assay revealed that EphA2 silencing significantly reduced the viability of both human and canine osteosarcoma cells when compared to matching non-silenced controls." (PMID 39056783, 2024). "These experiments showed that osteosarcoma cells were more sensitive to cisplatin after EphA2 silencing when compared to the non-silenced controls." (PMID 39056783, 2024). "Previous studies have shown that ephrin alpha 2 receptor (EphA2), a member of the Eph family of receptor tyrosine kinases, is highly expressed in osteosarcoma lines and primary osteosarcoma cells, but not in normal bone cells." (PMID 38433190, 2024). "The interaction between EPHA2 and ephrin-A1 enhanced the phosphorylation of EPHA2′s tyrosine and increased the mitogenic process via the Ras/MAPK pathway, which eventually enhanced the proliferation and migration of SaOS2 and MNNG/HOS human osteosarcoma cells." (PMID 35563562, 2022). "Another interesting data extracted from this study was that the phosphorylation of EPHA2 at its critical serine 897 contributes to the activation of the oncogenic non-canonical process in both osteosarcoma and chondrosarcoma patient-derived xenograft models." (PMID 35563562, 2022). "The activated phosphorylated form of EphA2 (p-EphA2S897) was displayed in osteosarcoma and chondrosarcoma but not in Ewing’s Sarcoma PDXs from our cohort." (PMID 34831119, 2021). "Anti-EphA2 CAR T intravenously infused in osteosarcoma, and Ewing’s sarcoma-bearing mice significantly improved their survival and eradicated metastatic deposits in liver and lungs in an aggressive metastatic osteosarcoma murine model." (PMID 34572932, 2021). "Moreover, deeply investigating the molecular perturbation evoked by pazopanib and trametinib combination, we identified EphA2, IL-7R, and MEK6 as potential novel targets in osteosarcoma." (PMID 32531992, 2020). "Finally, PDGFRα, Axl, PDGFRβ, RYK, EGFR, EphA2, EphA10 and IGF1-R are key targets of imatinib mesylate in osteosarcoma." (PMID 24599309, 2014).
osteosarcoma (continued). "Ephrin-A1 binding to EPHA2, which is not expressed in normal bone but is overexpressed in osteosarcoma, induces increased tyrosine phosphorylation and activation of downstream signaling pathways mediated by MAPK activation, possibly stimulating osteosarcoma’s metastatic potential." (PMID 38612645, 2024). "Furthermore, EPHA2 was present only in osteosarcoma samples but absent in non-malignant bone cells." (PMID 35563562, 2022). "Indeed, we showed that EphA2 targeting with the small molecule inhibitor ALW-II-41-27 resulted in marked reduction in cell growth and cell viability in four in vitro models, which we derived from primary osteosarcoma, Ewing’s sarcoma and chondrosarcoma tumor tissues." (PMID 34831119, 2021). "We believe that the data presented in this article warrant further studies in the field of osteosarcoma, Ewing’s sarcoma and, especially, chondrosarcoma, in which EphA2 pathway activation has not been previously reported and might represent a therapeutic opportunity for this disease." (PMID 34831119, 2021). "In particular, in both osteosarcoma PDX models, we showed EphA2 expression and phosphorylation at critical serine 897 (Ser897) residue, as a sign of oncogenic, non-canonical EphA2 pathway activation." (PMID 34831119, 2021).